AKR1C3 (aldo-keto reductase family 1 member C3)
Diseases named in the same sentence as AKR1C3 in open-access papers (continued):
Sharing a sentence is not in itself a finding about the gene and the disease.
hepatocellular carcinoma (15 papers, 2020 to 2026). A malignant tumor that arises from hepatocytes. "Experimental validation confirmed the upregulation of these hub genes in clinical tissues and demonstrated that ALDH2 and AKR1C3 promote hepatoma cell migration and invasion, providing experimental evidence for their potential roles in disease progression." (PMID 42136961, 2026). "AKR1C3, which plays a role in steroid metabolism and prostaglandin synthesis, has been shown to regulate ferroptosis in hepatocellular carcinoma (HCC) through the YAP/SLC7A11 signaling pathway." (PMID 39897029, 2025). "In hepatocellular carcinoma, the knockdown of AKR1C3 resulted in a decrease in YAP nuclear translocation, leading to the inhibition of cystine transporter SLC7A11." (PMID 38675549, 2024). "In hepatocellular carcinoma, AKR1C3 mediates the progression of ferroptosis by regulating the YAP/SLC7A11 signaling pathway, which is a novel treatment target for clinical therapy." (PMID 38577596, 2024). "Similarly, AKR1C3 facilitates hepatocellular carcinoma adaptation to sorafenib by promoting lipid droplet biogenesis, inhibiting autophagy, and reprogramming metabolic circuits." (PMID 40524207, 2025). "Thus, a Phase 2 study of single-agent OBI-3424 is currently enrolling patients with locally advanced/metastatic pancreatic cancer, hepatocellular cancer, or other epithelial carcinomas with tumoral AKR1C3 overexpression." (PMID 37173365, 2023). "In general, AKR1C3 expression and AR-signalling are related to the development of several malignancies (e.g., bladder cancer, renal cell carcinoma, hepatocellular cancer, and endometrial cancer), as well as ovarian, breast, and pancreatic cancers, all of which are therapeutic targets of olaparib." (PMID 33114555, 2020). "Inhibition of AKR1C3 activity can induce LDs catabolism, leading to mitochondrial division and apoptosis in sorafenib resistant hepatocellular carcinoma (HCC)." (PMID 41421797, 2025). "AKR1C3 inducing sorafenib resistance in hepatocellular carcinoma remains unclear." (PMID 35359392, 2022). "AKR1C3 participates in NF-κB signaling and IL6/STAT3 pathway, resulting in cell proliferation and metastasis in hepatocellular carcinoma (HCC) cells, while treatment with the AKR1C3 inhibitors could suppress tumor growth and promote cell death." (PMID 40603306, 2025). "Therefore, our study suggested that AKR1C3 and AKR1D1 might be candidates for hepatocellular carcinoma targeted therapy." (PMID 33493134, 2021).
colon cancer (9 papers, 2014 to 2025). "Li Yafei and colleagues identified ARID3A as a transcription factor for AKR1C3, inhibiting its expression in colon cancer cells." (PMID 38523637, 2024). "AKR1C3 is an aldo–keto reductase that has been described as responsible for gaining resistance against cisplatin treatment when overexpressed in colon cancer cells together with AKR1C1[Gene ID: 1645]." (PMID 26359356, 2015). "In colon cancer, AKR1C3 downregulation by ARID3A enhances 5-FU sensitivity." (PMID 41009436, 2025). "Moreover, the inhibition of AKR1C3 expression has been reported to promote an increase in ROS and a reversal of drug resistance to cisplatin in patients diagnosed with colon cancer." (PMID 34830394, 2021). "This interaction between AKR1C3 and ARID3A was associated with decreased chemosensitivity to 5-fluorouracil (5-FU) in colon cancer cells, suggesting that the ARID3A to AKR1C3 ratio may serve as a valuable marker for predicting the prognosis of colon cancer patients." (PMID 38523637, 2024). "In colon cancer, ARID3A, a transcriptional regulator, inhibits AKR1C3 transcription, leading to downregulation of AKR1C3." (PMID 38523637, 2024). "In the study of colon cancer, specific inhibitors of AKR1C1 and AKR1C3 or knockdowns of the genes in the resistant cells were used to resensitize the cells to cisplatin toxicity." (PMID 34830394, 2021). "In colon cancers, studies reported that the up-regulated expression of AKR1B10, AKR1C1, AKR1C2 and AKR1C3 contributed to chemotherapeutic drug resistance indirectly, by reducing oxidative stress generated by these chemotherapeutic agents." (PMID 27635343, 2016). "The resistance towards the chemotherapeutic drug cisplatin in colon cancers is believed to be a result of decreased sensitivity toward cellular damages evoked by oxidative stress-derived aldehydes, 4-hydroxy-2-nonenal and 4-oxo-2-nonenal, that are detoxified by AKR1C1 and AKR1C3." (PMID 25243088, 2014).
leukemia (9 papers, 2015 to 2026). A malignant (clonal) hematologic disorder, involving hematopoietic stem cells and characterized by the presence of primitive or atypical myeloid or lymphoid cells in the bone marrow and the blood. "This link between AKR1C3 and leukemia risk implicates a potential role of AKR1C3 in leukemogenesis." (PMID 35388063, 2022). "AKR1C3 is overexpressed in acute myeloid leukemia and T-cell acute lymphoblastic leukemia and confers chemotherapeutic resistance to anthracycline, which is the first-line agent for leukemia treatment." (PMID 36275721, 2022). "Moreover, AKR1C3 has been identified as a potential therapeutic target in leukemia because its PGD2 reductase activity may prevent cell differentiation." (PMID 25769101, 2015). "Many leukemia stem cell like genes of the LSC17 signature diminished after day 14 such as LAPTM4B, MMRN1, ADGRG1 or AKR1C3, but some were upregulated again by day 30, day 70 CD19- and/or day 70 CD19+." (PMID 41145673, 2026). "Particularly, AKR1C3 has become a recurrent target in cancer, as its expression correlates with anthracycline resistance, and its function in prostaglandin and sex hormone biosynthesis may promote oncological disorders like leukaemia and hormone-related tumours, respectively." (PMID 33322571, 2020). "Similarly, the key functions of AKR1C3 in the metabolism of prostaglandins and sex hormones have been related to the development of leukaemia and hormone-related tumours, respectively; thus, AKR1C3 targeting by BTK inhibitors may also counteract carcinogenesis in those tissues overexpressing AKR1C3." (PMID 33322571, 2020). "Therefore, by targeting AKR1C3, ZAN may affect both leukaemia- and hormone-dependent, as well as independent, cancers." (PMID 36297430, 2022).
bladder cancer (7 papers, 2013 to 2025). "A positive correlation was seen between the high expression of AKR1C3 and the risk of bladder cancer progression and mortality." (PMID 39055885, 2024). "Moreover, AKR1C3 rs12529 has also been associated with lung and bladder cancer risk." (PMID 23359804, 2013). "Meanwhile, the impact of aldo-keto reductase 1C3 (AKR1C3), an androgen-metabolizing enzyme involving the production of DHT, on chemoresistance has been explored in bladder cancer." (PMID 40486871, 2025). "A chromene derivative 2j, which could function as a selective inhibitor for AKR1C3, was found to inhibit the expression of AR and ELK1 in bladder cancer cells and enhance the cytotoxic activity of gemcitabine + cisplatin." (PMID 40486871, 2025).
endometrial cancer (7 papers, 2020 to 2024). Primary or metastatic malignant neoplasm involving the endometrium (mucous membrane that lines the endometrial cavity). "In various human cancers, AKR1C3 has exhibited upregulation, with particular significance in endometrial cancer, the most prevalent malignancy of the female genital tract." (PMID 38523637, 2024). "A study evaluated the level of AKR1C3 in endometrial cancer and ovarian cancer and examined possible correlations between expression of AKR1C3 and other clinical and pathological data." (PMID 34199169, 2021). "Using Mann–Whitney U tests and linear regression analysis, we also evaluated correlations between percentage of AKR1C3 positive cells and the clinical data of the patients with endometrial cancer." (PMID 33352741, 2020). "In endometrial cancer, increased AKR1C3 mRNA levels have been demonstrated in the model cell lines Ishikawa and HEC-1A versus the control HIEEC cell line." (PMID 33352741, 2020). "Notably, AKR1C3 expression was observed to be higher in endometrial cancer compared to ovarian cancer." (PMID 38523637, 2024). "AKR1C3 and its product PGF2α have been shown to control the development of prostate, breast, and endometrial carcinomas, respectively, but their role in HCC is largely unknown." (PMID 38188684, 2023). "As AKR1C3 catalyzes formation of the potent androgen which can activate androgen receptor and can thus inhibit proliferation this supports the hypothesis of the anti-proliferative role of AKR1C3 in endometrial cancer." (PMID 33352741, 2020). "For endometrial cancer, positive IHC reactions were seen for AKR1C3 in the cytoplasm and also nucleus of the epithelial cancer cells in endometrioid and nonendometrioid endometrial cancers, including serous, dedifferentiated, carcinosarcomas, clear cell, and mixed carcinoma." (PMID 33352741, 2020). "In this study, we evaluated the immunohistochemical (IHC) staining of AKR1C3 in 123 paraffin-embedded samples of endometrial cancer and 99 samples of ovarian cancer, and examined possible correlations between expression of AKR1C3 and other clinicopathological data." (PMID 33352741, 2020). "The potential protective effects of androgens in endometrial cancer might help to explain our results here, where higher AKR1C3 levels responsible for formation of active androgen, were associated with better cumulative and disease free survival of patients with endometrioid endometrial cancer." (PMID 33352741, 2020). "As far as gene expression changes are concerned, the Aldo-Keto Reductase family 1 member C3 (AKR1C3) was found to be upregulated, whereas both the Anterior Gradient Homolog 3 (AGR3) and the Nitric Oxide Synthase 2A (NOS2A) were seemingly downregulated in all three endometrial cancer cell lines." (PMID 37298140, 2023).
acute myeloid leukemia (6 papers, 2022 to 2025). Acute myeloid leukemia (AML) is a group of neoplasms arising from precursor cells committed to the myeloid cell-line differentiation. "There are potent and highly selective AKR1C3 inhibitors for the treatment of acute myeloid leukemia and T-ALL11,18." (PMID 35388063, 2022). "In acute myeloid leukaemia (AML), AKR1C3 also functions as a prostaglandin D2 11-ketoreductase involved in AML progression." (PMID 40905588, 2025). "AKR1C3 also plays a role in non-hormonal dependent malignancies, such as acute myeloid leukemia by its role in cell proliferation and differentiation via peroxisome proliferator activated receptor γ (PPARγ) signaling pathway." (PMID 35388063, 2022).
androgen excess (6 papers, 2017 to 2025). "The androgenic enzyme aldoketoreductase type 3 (AKR1C3) is expressed in subcutaneous adipose tissue and is stimulated by insulin to contribute to hyperandrogenism in obese women." (PMID 31616381, 2019). "AKR1C3 is a crucial enzyme in androgen biosynthesis in the adrenal, ovary, prostate, and adipose tissue, and AKR1C3 single nucleotide polymorphisms have been reported as associated with an increased prevalence of PCOS and hyperandrogenism in women." (PMID 28645211, 2017). "The increase in insulin level can up-regulate androgen levels, thereby inducing hyperandrogenism and up-regulating androgen levels in fatty tissues of PCOS patients via increased AKR1C3 activity." (PMID 36465612, 2022). "CpG hypomethylation in genes such as AKR1C3, GHRHR, MAMLD1 and RETN, and hypermethylation in TNF, which can indirectly contribute to androgen excess, were consistent with increased and decreased levels of the respective gene transcripts." (PMID 30975191, 2019). "Recent research has shown that CpG hypomethylation regarding GHRHR, AKR1C3, RETN, and MAMLD1 and hypermethylation regarding TNF, which can indirectly contribute to androgen excess, were consistent with increased and decreased levels of the corresponding gene transcripts, respectively." (PMID 33763111, 2021).
esophageal adenocarcinoma (6 papers, 2021 to 2025). A malignant tumor with glandular differentiation arising predominantly from Barrett mucosa in the lower third of the esophagus. "One such moonlighting function was found in esophageal adenocarcinoma where AKR1C3 regulates AKT phosphorylation, leading to chemotherapy resistance." (PMID 37240349, 2023). "Data from GSE26886 showed that AKR1C3 is upregulated in Barrett’s esophagus (a precursor lesion of EAC), EAC and ESCC as compared to squamous epithelium." (PMID 34065695, 2021). "The previous study indicated that knockdown AKR1C3 in esophageal adenocarcinoma cells exhibited greater apoptosis upon receiving cisplatin treatment." (PMID 34830394, 2021). "AKT phosphorylation was regulated by AKR1C3 and might be responsible for eliminating over-produced ROS in esophageal adenocarcinoma (EAC) cells." (PMID 35359392, 2022). "The inconsistent expression of AKR1C3 in our cohort might be explained by the possibility that some of the esophageal biopsies are Barrett’s esophagus in our cohort." (PMID 34065695, 2021).
esophageal cancer (6 papers, 2014 to 2025). A primary or metastatic malignant neoplasm involving the esophagus. "Furthermore, these data confirmed the results of our previous work in esophageal cancer, showing AKR1C3 could also cause radioresistance in PCa, besides esophageal cancer and NSCLC." (PMID 27385003, 2016). "From the TCGA database, we found AKR1C3 was upregulated in tumor tissues compared to the adjacent normal tissues in esophageal cancer patients." (PMID 40603306, 2025). "These clinical observations suggest that elevated levels of expression of AKR1C3 lead to radioresistance in tumors other than esophageal cancer." (PMID 25419901, 2014). "In this study, we found that the acquiring of radioresistance coincided with elevated expression of AKR1C3 in esophageal cancer cells, and suppression of AKR1C3 expression restored the sensitivity of the acquired tumor cells and xenograft animals to ionizing radiation (IR)." (PMID 25419901, 2014). "Clearly, a strong correlation (p <0.017) exists between elevated expression of AKR1C3 and radioresistance of esophageal carcinoma, implying that AKR1C3 might be a prognostic marker for cancer radiotherapy." (PMID 25419901, 2014). "The close relevance of AKR1C3 and radioresistance observed in esophageal carcinomas might have significant impact on cancer target therapy." (PMID 25419901, 2014). "Our study suggests that AKR1C3 might share the same properties as antioxidant enzymes in alleviation of ROS accumulation in tumor cells and may serve as a potential biomarker for predicting prognosis of radiotherapy and even direct a targeted therapy for esophageal cancer and other tumors." (PMID 25419901, 2014). "Collectively, we explored the non-radioresistant vs. resistant esophageal cancer cells and found the coincidence of differentiation of AKR1C3 expression, cellular ROS level/DNA damage and acquired radioresistance." (PMID 25419901, 2014). "AKR1C3 is a radiation resistance gene in esophageal cancer and non-smal-celll lung cancer." (PMID 27385003, 2016).
glioma (6 papers, 2008 to 2023). A benign or malignant brain and spinal cord tumor that arises from glial cells (astrocytes, oligodendrocytes, ependymal cells). "This confirmed that gliomas with 1p19q codeletion overexpressed neuronal/normal brain genes (AKR1C3, C20orf42, CTTNBP2, L1CAM, GALNT13) as well as genes implicated in gliogenesis and neurogenesis (OLIG2, BMP2, NOG, DCX, ATOH8)." (PMID 18492260, 2008). "The 89-gene signature consists of a number of hypoxia and inflammation-related genes such as AKR1C3, PTX3, PLAT and IGFBP2, showing that these two inseparable hallmarks are involved in tumor progression and play significant roles in glioma pathogenesis." (PMID 27323413, 2016). "Several aldo-keto reductases are responsible for the metabolization of oxcarbazepine (AKR1C1, AKR1C2, AKR1C3, and AKR1C4), which have not been found to be expressed in the brain or in gliomas." (PMID 37190109, 2023). "Since the enzymes responsible for the metabolization of oxcarbazepine (AKR1C1, AKR1C2, AKR1C3, and AKR1C4) are highly expressed in hepatocytes but not in glioma cells, we expect only marginal transformation to MHD in our in vitro proliferation assay." (PMID 37190109, 2023).
melanoma (6 papers, 2016 to 2022). A malignant, usually aggressive tumor composed of atypical, neoplastic melanocytes. "Mutation frequency of TBXAS1, PTGIS, AKR1C3, PTGDR, PTGFR and PTGER3 genes in melanoma were 5–6%, 5–7%, 2.8–5%, 3–4%, 7–9%, 2.1–5%, respectively." (PMID 35453789, 2022). "muTARGET web-based tool allowed us to predict genes, which expression patterns can be associated with genetic polymorphism in group #1 (TBXAS1, PTGIS, and AKR1C3) or group #2 (PTGDR, PTGFR, and PTGER3) in melanoma." (PMID 35453789, 2022). "Inhibition of ALOX15 contributes to abrogation of lipid peroxides accumulation; thus, ferroptosis resistant melanoma cells efficiently activate NRF2 to elevate the level of AKR1C3 and lead to a negative regulation of ALOX15." (PMID 34284753, 2021). "Recent studies suggested that aldo-keto reductases (AKRs), a superfamily of NADPH-linked oxidoreductases, including AKR1C1, AKR1C2, and AKR1C3, are potential NFE2L2 target genes responsible for ferroptosis resistance via inhibiting lipid peroxidation in melanoma cells." (PMID 34938739, 2021). "Thus, genes controlling the turnover of vitamin D (CYP27B1, CYP24A1), vitamin A (ALDH1A3, AKR1B10), and cholesterol (CYP7B1), were up-regulated in psoriasis, whereas melanomas showed downregulation of genes regulating turnover of vitamin A (AKR1C3), and cholesterol (CYP39A1)." (PMID 26901218, 2016).
Obesity (6 papers, 2017 to 2025). Accumulation of substantial excess body fat. "AKR1C3 expression is increased in adipose tissue from patients with simple obesity and decreases with weight loss; furthermore, AKR1C3 expression in adipose tissue from PCOS patients is higher than in body mass index (BMI)-matched controls." (PMID 28566439, 2017). "On the other hand, the production of 11-oxygenated androgens increases in obesity as their production are stimulated by aldo–keto reductase 1C3 (AKR1C3) which is expressed in adipose tissue." (PMID 38498076, 2024). "Abnormal expression of AKR1C3 is important for the development of obesity, NIDDM, and insulin resistance." (PMID 30678306, 2019). "Specifically, the androgen-activating enzyme aldoketoreductase type 1C3 (AKR1C3), generates testosterone from the androgenic precursor androstenedione, is abundantly expressed in AT and its SAT expression is induced in obesity, PCOS, and hyperinsulinaemia." (PMID 35049520, 2022).
Insulin resistance (5 papers, 2017 to 2025). Increased resistance towards insulin, that is, diminished effectiveness of insulin in reducing blood glucose levels. "Further, it has been proposed that androgens activated by adipose tissue mediated by AKR1C3 also increased lipid synthesis that provokes lipotoxicity, which in turn is involved in insulin resistance progression." (PMID 38498076, 2024). "In our in vitro studies, we conclusively demonstrated that AKR1C3 expression is regulated by insulin, mechanistically linking AE and insulin resistance, the two major metabolic features in PCOS." (PMID 28645211, 2017). "We have described putative mechanisms by which androgens regulate adipose tissue function, lipid metabolism, and fat mass and have highlighted, at the level of the adipocyte, the enzyme AKR1C3 as a key regulator linking insulin resistance and AE in PCOS." (PMID 28645211, 2017). "Hence, disruption of AKR1C3-mediated androgen generation ameliorates androgen-mediated adverse effects on adipocyte lipogenesis, thereby mechanistically linking AE and insulin resistance." (PMID 28645211, 2017).